IL15 (interleukin 15)
Diseases named in the same sentence as IL15 in open-access papers (continued):
Sharing a sentence is not in itself a finding about the gene and the disease.
tumor (continued). "Conversely, reconstitution of IL-15 expression selectively in CD11c+ DCs restored NK cells and CD8+ T-cell compartments, with a subsequent reduction in tumor burden." (PMID 34884543, 2021). "Modification of IL-15 activated CIK cells by lentiviral CAR transduction and its influence on proliferation, phenotype, anti-tumor ability, cytokine secretion, and alloreactivity in vitro was previously published by our group." (PMID 33193388, 2020). "With the combination of IL-15 and CD44-targeted NIR-PIT, the number of Gzmb-positive CD8 T cells in the tumor tissue significantly increased at day 7 after the therapy." (PMID 32927646, 2020). "Comparing with the single-agent therapy, the combination therapy of IL-15 after NIR-PIT inhibited tumor growth, prolonged survival, and increased tumor infiltrating CD8+ T cells more efficiently in tumor-bearing mice." (PMID 32927646, 2020). "The HATMSC2-MVs used in this study affect both histologically different cell lines, the ES-2 cells and the OAW-42 cells, by increasing the production of tumor-suppressive cytokines, such as IL-1ra, IL-2, IL-2Ra, IL-12-p40, IL12-p70, IL-15, and IFN-γ." (PMID 33266317, 2020). "Tumor-bearing mice receiving IL-15 with antibodies to CTLA-4 and PD-L1 manifested marked prolongation of survival compared to mice receiving IL-15 with either agent alone." (PMID 32508818, 2020). "The combination of the NK cell-activating interleukin IL-15 and therapeutic antibodies, which engaged the co-stimulatory receptor CD40, improved anti-tumor responses in Panc02 or KPC mouse tumor models." (PMID 33022971, 2020). "This study suggested that the IL-15-conjugated CD28-CAR structure reduced the exhaustion marker and improved the persistence and the tumor-killing activity of NKT-established CARs." (PMID 33322408, 2020). "To assess cytotoxic activity of cytokine-treated NK cells, we co-cultured IL-2/IL-15-treated NK cells (E) and green fluorescent protein (GFP)-labeled GBM tumor cells (T) at different ratios." (PMID 32218162, 2020). "Three syngeneic mouse tumor models, MC38-luc, LL/2, and MOC1, underwent combined CD44-targeted NIR-PIT and short-term IL-15 administration with appropriate controls." (PMID 32927646, 2020). "Adoptive immunotherapy with CD8+ T lymphocytes isolated from 47-LDA-immunized and cured mice, in combination with plasmid-derived interleukin 15 (IL-15) and IL-21, led to regression of NXS2 tumors and prolonged tumor-free survival." (PMID 32075083, 2020). "The combination of IL-15 administration and CD44-targeted NIR-PIT showed superiority in survival to IL-15 treatment alone in all three tumor types tested here." (PMID 32927646, 2020). "In a mouse model, we have observed activation of ULBP1, IL-15, Killer/DR5 and Fas/Apo1 in B16 tumor cells specifically in response to combined p19Arf+mIFNβ gene transfer." (PMID 33193370, 2020). "Accordingly, cytokines like IL-2, IL-7, IL-15, and IL-21 are fundamental both for generation of the ACT cell products and to increase the efficacy and the duration of the anti-tumor response in vivo." (PMID 32973794, 2020). "Pre-clinical data showed that CD28 co-stimulation and co-expression of IL-15 yielded the best CAR cell durability, relocation to tumor sites, and tumor control in murine neuroblastoma and lymphoma models, while inducing no symptoms of GvHD." (PMID 32429316, 2020). "One interesting approach can be the co-activation of macrophages (MΦs) (retinoic acid), NK cells (IL-15, IL-22, and IL-23), cytotoxic T cells (CTLs) (IL-2, TNF-α, IFN-γ), and the acquisition and presentation of tumor antigens by dendritic cells." (PMID 33276556, 2020). "The expression of lower levels of IL-15 in the tumors generated higher levels of the anti-tumor cytokines IFN-γ and MIP-1β than what was generated when higher levels of IL-15 were obtained." (PMID 33096755, 2020). "IL-15 plays a crucial role in T and NKT cells via enhanced CAR antitumor activity and survival in peripheral blood and tumor tissue." (PMID 33322408, 2020).
tumor (continued). "IL-15 increased the expression of CIS, a checkpoint of NK cell mediated tumor immunity as well as SOCS1 that attenuates IL-15 receptor signaling by CD8+ CD44hi memory T lymphocytes." (PMID 32508818, 2020). "In the context of supporting immune cell persistence in the immunosuppressive tumor microenvironment (TME), IL-2 and IL-15 have different potency in terms of regulating signaling pathway and protein synthesis." (PMID 33266177, 2020). "Our results suggest that tumor-induced arrest of DN2 T cells in the thymus is correlated with a significant increase in il-10 transcription and a coordinated reduction in il-7 and il-15 transcription." (PMID 32582141, 2020). "In summary, we show here that the combination of IL‐15 and CD40 agonist therapy has profound anti‐tumor activities and combining both agents leads to significant synergistic effects." (PMID 32821382, 2020). "We recently showed that the expression of soluble γc receptor (sγc) in T cells is highly upregulated upon TCR stimulation and inhibits the anti-tumor response of CD8+ T cells via regulating IL-2 and IL-15 signaling." (PMID 32731404, 2020). "This TriKE was designed to attract CD19+ tumor cells to CD16+ NK cells, whereas IL-15 sustained the proliferation, development, and survival of NK cells." (PMID 33299651, 2020). "The mAb-mediated clearance of soluble MIC has shown promising synergy with the IL-15 agonist ALT-803 mAb and enhanced anti-tumour responses with anti-CTLA4 checkpoint blockade therapy in clinically relevant models." (PMID 30626155, 2019). "N-803, formerly ALT-803, is an IL-15 superagonist mutant and dimeric IL-15RαSushi-Fc fusion protein complex that enhances CD8+ T and NK cell expansion and function and exhibits anti-tumor efficacy in preclinical models." (PMID 30898149, 2019). "Looking into the overall role of CD56 in immune effector functions, we were able to establish a direct involvement of CD56 in the cytotoxic capacity of IL-15 DCs, NK cells, and γδ T cells against CD56+ tumor cells." (PMID 31336622, 2019). "The CD56+ immune cells (IL-15 DCs, NK cells, and γδ T cells) were captured too interacting with CD56+ tumor cells by means of a CD56 homophilic binding, whereby an accumulation of red signal (CD56–CD56 interaction) was observed." (PMID 31336622, 2019). "It was reported that the central memory T cells showed higher anti-tumor toxicity than the effector memory T cells in vivo, and the stimulation by combined anti-CD3, anti-CD28, IL-7 and IL-15 was reported to improve T cell specific cytotoxicity." (PMID 31044002, 2019). "For example, IL-15 can convert central memory γδ T cells into potent CD56+ effector cells with the ability to rapidly produce large amounts of interferon-γ and kill tumor cells." (PMID 31336622, 2019). "After establishment of tumor xenografts, mice were injected with PBS, SG400-EGFP, SG400-E2F1, and SG400-E2F/IL-15." (PMID 31278126, 2019). "The IL-15/IL15 receptor α complex showed synergy and improved anti-tumor effects when combined with anti-CTLA4 and anti-PD-L1 ICI." (PMID 31614774, 2019). "In CT26 tumor bearing mice, TAT-survivin-IL-15 vaccination was more efficacious than TAT-survivin vaccination." (PMID 29508006, 2018). "IL-15 is important for maintaining memory CD8+ T cells and NK cells and is being used in cancer treatments to increase NK cell-mediated anti-tumor activity." (PMID 30557313, 2018). "Deep IL-15 was evaluated in an adoptive T cell therapy model by treatment of B16-F10 tumor-bearing mice with PMEL CD8+ T (PMEL) cells (10-27 x 106), carrying up to 158 μg of Deep IL-15 (>15-fold the maximum tolerated dose, MTD, of IL15-Fc)." (PMID 30400835, 2018). "On the other hand, when IL-15 DCs were added together with signals of malignancy (presence of IPP and tumor cells) a strong IFN-γ response was observed in γδ T cells." (PMID 29692776, 2018).
tumor (continued). "This fusion protein targeted the NKG2DL-positive tumor cells through its NKG2D domains and presented IL-15 to NK or CD8+ T cells to promote their activation and cytotoxicity to tumor cells." (PMID 29316666, 2018). "Preclinical and clinical studies suggest that the immune effects of tumor-directed vaccine, PD-L1 blockade, TGF-β sequestration, IL-15 agonism, and IDO1 inhibition can be additive and/or synergistic." (PMID 30227893, 2018). "Many studies have shown that MSCs engineered to express anti-tumour cytokines, such as interleukin-2 (IL-2), interferon-beta (IFN-β), TRAIL, and IL-15, are able to deliver these ligands directly to the tumour site and to efficiently induce tumour regression." (PMID 30060445, 2018). "Many cytokines, like IL-2, IL-15 and IL-21 were chosen to fuse with NKG2D because of their ability to promote immune cell functions and induce anti-tumor responses." (PMID 29316666, 2018). "Particularly, IL-15 is a cytokine that primarily stimulates the proliferation and cytotoxic functions of CD8 T lymphocytes and NK cells, resulting in enhanced anti-tumor responses." (PMID 30060526, 2018). "In contrast, tumor suppressive mediators made up most inversely correlated genes, e.g. CXCL10, CXCL11, IL15, TNFSF10/TRAIL, and TNFSF14/LIGHT." (PMID 29141914, 2018). "Efforts to overcome primary or secondary resistance thus include multi or tandem CAR T cells targeting two different tumor antigens (e. g., CD19 and CD22), or the use of checkpoint inhibitors or interleukin-15 to reactivate exhausted CAR T cells." (PMID 29983827, 2018). "Armoring CAR-Ts to produce interleukin-15 (IL15) or interleukin-12 (IL12) has been shown to drive CAR-T expansion and resistance to immunosuppression, respectively, enhancing anti-tumor activity." (PMID 30400835, 2018). "In line with our observations in humans, DCs cultured with HPV-like particle matured more efficiently in the presence of IL-15, and this correlated with enhanced NK cell activation and killing of HPV-infected tumor cells." (PMID 29491009, 2018). "In accordance with this modulation of gene expression, IL-15 treatment also reduced the amount of CD68+ and F4/80+/CD68+ cells in the tumor mass, indicative of reduced activation of GAMs." (PMID 29286001, 2017). "For example, the cytokine IL-15 exhibits biological activity similar of IL-2 in that it enhances proliferation of CD8+CTL and natural killer (NK) cells, which in turn kill tumor cells." (PMID 29296227, 2017). "In multivariate analysis, tumor thrombus, UCSF criteria, and recipient IL-15 rs10519613 genotypes were independent predictive factors of HCC recurrence after LT." (PMID 29162948, 2017). "Univariate Cox regression analysis revealed that histologic grade, tumor size, tumor thrombus, TMN stage, UCSF criteria, recipient IL-15 rs10519613 genotypes (CA/AA versus CC) were significantly associated with DFS and OS." (PMID 29162948, 2017). "Briefly, IL-12, IL-17, GM-CSF, MIP-1α, IL-5, IFN-γ, IL-1Rα, IL-7, IP-10, IL-2R, IL-4,IL-15,MIP-1β levels were higher in the inflammation group and kept relative lower level in healthy and tumor groups." (PMID 28977824, 2017). "Both human IL-15 (200 μg/kg) and murine IL-15 (3 g/kg) treatment promote CD215+ myeloid cells in B16F10-bearing C57BL/6 mice, and these CD215+ myeloid cells were sorted and shown to promote tumor growth in cell culture systems." (PMID 29255466, 2017). "Our findings demonstrate that IL-15 induced CD215+ myeloid cell proliferation and that these myeloid cells promoted tumor growth." (PMID 29255466, 2017). "CART cells exposed to IL-2 or IL-15 lysed SKOV3 cells more efficiently than those exposed to IL-18 or NC, even at the lowest T cell to tumor ratio." (PMID 27409425, 2016). "IL-15 has been shown to increase CD8+ T memory cell function and increase T cell anti-tumor activity." (PMID 26999211, 2016).
tumor (continued). "IL-15 provided similar performance in stimulating CART cell expansion and tumor-lysis functions in vitro than IL-2, but induced a less differentiated phenotype, with higher CD27 and CD28 expression." (PMID 27409425, 2016). "Therefore, we share their view on the need of caution and propose that the clinical administration of recombinant IL15 alone could be efficient and sufficient in NK cell-mediated tumor eradication thus avoiding potentially immunostimulatory molecules generated by the combination of IL15Rα with IL15." (PMID 26822794, 2016). "IL-2 and IL-15-exposed CART cells secreted more proinflammatory cytokines and presented stronger tumor-lysis ability in vitro." (PMID 27409425, 2016). "IL-15 DCs can be obtained by culturing monocytes from blood in IL-15 instead of IL-4 in standard protocols, and the resulting DCs have an increased capacity to stimulate NK cells cytotoxicity, which could be a crucial contribution in anti-tumor efficacy of DC vaccines." (PMID 28536377, 2016). "Later, they inserted IL-15 gene into the E3 region of the adenovirus and found that human IL-15 expressing oncolytic adenovirus (Ad-E2F/IL15) showed stronger anti-tumor effect than simple oncolytic viruses (Ad-E2F)." (PMID 26980708, 2016). "Here, we determined the in vivo therapeutic effect of an antibody co-targeting sMIC with the immunostimulatory IL-15 superagonist complex, ALT-803, using genetically engineered transplantable syngeneic sMIC+ tumor models." (PMID 26625316, 2016). "A recent study has shown that anti-PD-L1 antibody treatment in combination with IL-15 reduces PD-1 expression on CD8+ T cells in murine metastatic colon cancer resulting in enhanced IFN-γ secretion and prolonged survival of tumor bearing animals." (PMID 27050669, 2016). "In contrast, the administration of IL-15 and IL-21 in combination with CART cells in vivo increased their tumor killing capacity." (PMID 27409425, 2016). "We show by immunofluorescent labelling that monolayers display phenotypic similarities with corresponding sphere cultures and primary tumours, and secrete clinically relevant inflammatory factors, including PGE2, VEGF, IL-6, IL-8 and IL-15." (PMID 26183281, 2015). "Increased levels of IL-15 and RANTES were found at the tumour site in mice inoculated with neuroblastoma cells." (PMID 26633468, 2015). "While studies have clearly demonstrated that IL-15 is critical for enhanced anti-tumor responses in mouse models of adoptive transfer there are currently no models to discern whether these IL-15-mediated responses are due to transpresented IL-15 or sIL-15 complexes." (PMID 25756182, 2015). "To determine which cell type(s) were responsible for anti-tumor responses in IL-15 TG/MT mice, we performed long term antibody depletion experiments with anti-NK1.1 or anti-CD8α antibody in IL-15 TG/MT mice." (PMID 25879689, 2015). "In this study, we assess the effects of the HPV vaccine and its individual components on the phenotype and function of IL-15 DC and DC-stimulated NK cells with specific attention for the cytotoxic activity of both cell types against HPV-positive tumour cells." (PMID 24979331, 2014). "Next, we demonstrate that vaccine-exposed IL-15 DC in turn induce phenotypic activation of NK cells, resulting in a synergistic cytotoxic action against HPV-infected tumour cells." (PMID 24979331, 2014). "Tumor sections of mice treated with the virus expressing IL15Rα-IL15 fusion protein showed dramatic and significant increase in numbers of infiltrating NK cells, compared to vMyx-tdTr and PBS treated tumor." (PMID 25329832, 2014). "Our data confirm that IL-2 and IL-15 improve CD8+ T cell activation and induction of prophylactic tumor immunity, also when incorporated in a coronavirus-based vaccine that delivers the cytokines directly to DCs in vivo." (PMID 24312302, 2013).
tumor (continued). "In many of these studies decreased tumor burden and prolonged survival was abolished when mice were depleted of NK and/or CD8+ T cells, demonstrating these IL-15 responsive effector cells were providing the anti-tumor effects." (PMID 24312353, 2013). "More importantly, IL-15 and IL-2 treatment overcame ligand-induced NKG2D downregulation, enabling NK cells to exhibit substantially enhanced cytotoxicity against tumor cells." (PMID 22629344, 2012). "In this study, IL-15 DCs are shown to possess potent tumor antigen presentation function in combination with lytic potential against the classical NK cell target cell line K562, thus confirming the hypothesis that IL-15 DCs qualify for the designation of killer DCs." (PMID 23284789, 2012). "In order to better understand the functions of the cytokine, we propose to study the IL-15/IL15R system on human kidney epithelial cells of normal origin (RPTEC) and on cells of tumor origin (RCC)." (PMID 22363690, 2012). "Monocytes/dendritic cells appear to mediate an NK cell supportive “homeostatic environment” potentially facilitating NK cells engraftment mediated by IL-15 following-APHSCT, ultimately leading to a therapeutic autologous graft-versus-tumor effect." (PMID 20414345, 2010). "CD8 T cells expanded in IL-15 have a survival advantage over IL-2 generated CD8 effector T cells and IL-15 induced central memory cells show more effective tumor control than IL-2 generated effector T cells." (PMID 20543982, 2010). "From a functional standpoint, IL-21/IL-15-treated cells secreted copious amounts of IFN-γ, GM-CSF and CCL3/MIP-1α, and expressed cell surface CD107a upon contact with NK-sensitive tumour targets, a measure of exocytosis of NK secretory granules." (PMID 19712464, 2009). "Pre-complexed IL-15-sIL-15Rα increases NK and CD8+ T-cell proliferation and anti-tumour activity up to 50 times compared to IL-15 alone." (PMID 19690616, 2009). "Finally, the NK cells differentiated with IL-15 and IL-21 underwent exocytosis of secretory granules, as measured by a flow cytometry-based CD107a degranulation assay, upon co-culturing for 4 hours with NK-sensitive tumour cell targets, indicating the acquisition of cytolytic potential." (PMID 19712464, 2009). "With the growing body of evidence supporting the anti-tumor effects of NK and NKT cells, it would be beneficial to examine the effects of exogenously administered NK activators such as IL-15 or toll-like receptor ligands on tumor prevention and treatment." (PMID 20027308, 2009). "Indeed, IL-15 treatment partly inhibited skeletal muscle wasting in AH-130-bearing rats by decreasing (8-fold) protein degradative rates (as measured by14C-bicarbonate pre-loading of muscle proteins) to values even lower than those observed in non-tumour-bearing animals." (PMID 10945502, 2000). "Mechanistically, lymphodepletion eliminates immunosuppressive cell populations and reduces competition for homeostatic cytokines such as IL-7 and IL-15, thereby fostering a cytokine-enriched milieu that supports CAR-T proliferation, survival, and early tumor clearance." (PMID 41596556, 2026). "Similarly, in neuroblastoma, an oncolytic adenovirus expressing RANTES and IL-15 in combination with GD2-specific CAR-T cells significantly improved CAR-T cell trafficking, survival, and anti-tumour efficacy." (PMID 40624498, 2025). "In particular, the delivery of IL-15 and the suppression of immunosuppressive mediators such as PGE2 and TGF-β by DC-Vesicles could prolong lymphocyte persistence and improve tumor infiltration." (PMID 40564018, 2025). "Altered molecular targets, such as E-cadherin (CDH1), MMP9, Survivin (BIRC5), Cytokeratin 5 (KRT5), VEGFA, IL15, TNF-α (TNF), TRAIL (TNFSF10), and Tenascin-C (TNC), exhibited increased expression in our study, which correlates with their upregulation in tumor samples from individuals with OC." (PMID 40072102, 2025).